LMNTD2 (lamin tail domain containing 2)
Synonyms: C11orf35; MGC35138
Tractability: No criterion of Open Targets' tractability assessment is met for any kind of drug.
Gene: Protein-coding gene on chromosome 11 (554,850 to 560,738, reverse strand). Ensembl gene ENSG00000185522.
Subcellular location (Human Protein Atlas): Cytoplasmic bodies
Gene Ontology:
Molecular function: protein binding; structural constituent of chromatin
Cellular component: lamin filament
Genetic constraint (gnomAD): Loss-of-function variants: 83 observed, 56.78 expected, observed/expected ratio (o/e) 1.46, 90% interval 1.22 to 1.75. The synonymous counts are far from expectation, so gnomAD's model fits this gene poorly and the ratio says little. Missense variants: 1,153 observed, 748.39 expected, observed/expected ratio (o/e) 1.54, 90% interval 1.47 to 1.62. Synonymous variants: 534 observed, 325.9 expected, observed/expected ratio (o/e) 1.64, 90% interval 1.53 to 1.76.
Homologues: Orthologues: chimpanzee LMNTD2 (97% identical), macaque LMNTD2 (89% identical), dog LMNTD2 (56% identical), pig LMNTD2 (54% identical), mouse Lmntd2 (50% identical), rat Lmntd2 (50% identical), Caenorhabditis elegans F10C1.9 (8% identical).